TRPS1 (transcriptional repressor GATA binding 1)
Diseases named in the same sentence as TRPS1 in open-access papers (continued):
Sharing a sentence is not in itself a finding about the gene and the disease.
cancer (continued). "It has previously been reported that TRPS1 plays a role in cancer development, and that higher levels of TRPS1 improved survival." (PMID 28841835, 2017). "The ER+ BCC lines that express both Cath-D and TRPS1 were derived from luminal-like cancer subtypes with a more differentiated epithelial-like phenotype, frequently associated with the absence of EMT." (PMID 26183398, 2015). "Overall, our study proposes that TRPS1 acts as a central hub in the control of cell cycle and proliferation during cancer development." (PMID 25277197, 2014). "Here, we sought to ascertain a role for TRPS1 in cell cycle control and cell proliferation in cancer cells and tissue samples." (PMID 25277197, 2014). "Moderate nuclear staining for TRPS1 was noted in cancer cells." (PMID 40025593, 2025). "This study aims to evaluate the utility of TRPS1 for establishing carcinoma of mammary origin." (PMID 40025593, 2025). "Additionally, we will explore TRPS1 expression in other cancers, compare various TRPS1 antibody clones used in clinical practice, and address the pitfalls and challenges associated with its diagnostic application." (PMID 39518009, 2024). "To evaluate whether it could be a target for cancer therapy, we investigated TRPS1 function in the healthy adult mammary gland using a conditional ubiquitous depletion mouse model where long-term depletion does not affect fitness." (PMID 38702730, 2024). "TRPS1 shares a structural homology with GATA transcription factors, and while its expression is more restricted to breast tissues, there is a risk of cross-reactivity with other cancers, especially when using less specific clones." (PMID 39518009, 2024). "In addition, we explored the interactions of the PR/TRPS1/HDAC2 complex after MPA treatment in cancer cell lines." (PMID 37344459, 2023). "Interestingly, we found that AF178030.2 can directly bind with trichorhinophalangeal syndrome-1 (TRPS1), an important regulator in epithelial-mesenchymal transition, which was found to be one of the main reasons to induce drug resistance in many cancers." (PMID 35399640, 2022). "High expression rates of TRPS1 can be observed in a variety of cancer tissues." (PMID 36626444, 2022). "How TRPS1 contributes to cancer metastasis needs to be further investigated." (PMID 30071870, 2018). "Given the relative paucity of information concerning TRPS1 during cell proliferation as compared with its role in other aspects of cancer, we first sought to assess the role of this transcriptional repressor in cell proliferation and cell cycle using an siRNA approach." (PMID 25277197, 2014). "Both the NF-κB/IL6/JAK2/STAT3 cascade, which we show here is modulated by miR-221/222-mediated downregulation of ADIPOR1, and ZEB2 expression, which we have previously shown is repressed by TRPS1, are well-characterized effector pathways in cancer metastasis, invasion, and EMT." (PMID 23776679, 2013). "Therefore, we rationally hypothesized that elevated TRPS1 expression in BC cells may promote cancer cell insensitivity to DNA-damaging agents by promoting robust DNA repair." (PMID 39276941, 2024). "Therefore, we speculate that TRPS1 may be used as a new cancer marker that provides a reference for judging the prognostic value of patients suffering from OS." (PMID 36238488, 2022). "Although numerous studies have reported that tricho-rhino-phalangeal syndrome type I (TRPS1) protein, the only reported atypical GATA transcription factor, is overexpressed in various carcinomas, the underlying mechanism(s) by which it contributes to cancer remain unknown." (PMID 30071870, 2018). "Excisional biopsy confirmed poorly differentiated carcinoma; immunohistochemistry (IHC) was positive for PanCK, CK7, TRPS1, and PAX8 with a high Ki-67 index (70%)." (PMID 40656412, 2025).
cancer (continued). "In summary, we confirmed our previously identified methylation biomarkers ALOX5, TRPS1 and Chromosome 16 as well as our protein biomarkers CXCL16 and TGFBI to discriminate UCa from cancer-free controls in a large and independent collective." (PMID 39587670, 2024). "The addition of RANKL promoted cell viability more significantly in Ishikawa than that in Ishikawa-TRPS1, while MPA treatment impaired the cancer-promoting effect of RANKL on both cells." (PMID 37344459, 2023). "EMT is an important process in the control of metastasis, and previous studies have shown that TRPS1 modulates EMT in prostate and breast cancers." (PMID 25277197, 2014). "Our results identified TRPS1 as a novel cofactor of PR-dependent recruitment by specifically binding to HDAC2, a member of corepressor complex, changing acetylation levels of the target gene RANKL, inducing its different expressions in different cancer cells." (PMID 37344459, 2023). "In the Cancer Dependency Map (depmap.org), the top FOXA1 co-dependencies from the CRISPR screen data (AVANA) by Pearson correlation are SPDEF followed by ESR1 (estrogen receptor alpha) and TRPS1, underscoring the critical interplay of FOXA1 and ESR134." (PMID 33980863, 2021). "Mice bearing Trps1 sgRNA, but not those bearing scrambled sgRNA, were resistant to ectopic cancer." (PMID 38474078, 2024). "However, in BC, after MPA treatment, TRPS1 was identified as a transcription coactivator, PR recruited TRPS1 but did not interact with HDAC2 in the specific breast cell context, thus accelerating the acetylation of RANKL and enhancing the cancer-promoting effect of MPA." (PMID 37344459, 2023). "However, the mechanism by which TRPS1 contributes to cancer is not clear." (PMID 30071870, 2018). "However, low expression of TRPS-1 was detected in senescent BMECs cells, implying that expression of TRPS-1 could be regulated by the cellular growth state, and TRPS-1 protein probably has other function that differs from its function in cancer cells." (PMID 20969773, 2010).
skeletal dysplasia (4 papers, 2012 to 2023). Any Mendelian diseases that affects growth and development of the skeleton. "This rare inherited skeletal dysplasia is caused by mutations in the TRPS1 gene coding for the TRPS1 transcription factor." (PMID 35573139, 2022).
cardiovascular disease (1 paper, 2026). "Recent reports have shown that polymorphisms in the TRPS1 and TRIB1 genes are associated with plasma lipid levels and the risk of cardiovascular disease." (PMID 41972583, 2026).
epithelial neoplasm (1 paper, 2024). A benign or malignant neoplasm that arises from and is composed of epithelial cells. "By extending beyond previous research primarily focused on epithelial neoplasms, we have highlighted the importance of recognizing potential pitfalls associated with the use of TRPS1 IHC one should be aware of during dermatopathology practice." (PMID 39051323, 2024).
TRPS1 also shares sentences with these, for which no sentence is quoted: bladder cancer (2 papers); malnutrition (2); oral cancer (2); Abdominal obesity (1); acute coronary syndrome (1); adenocarcinoma of the appendix (1); Alopecia universalis (1); bladder urothelial carcinoma (1); breast angiosarcoma (1); cervical carcinoma (1); colorectal adenocarcinoma (1); Cornelia de Lange syndrome (1); cutaneous carcinoma in situ (1); cylindromas (1); dermatofibromas (1); dermatofibrosarcoma protuberans (1); ductal carcinoma (1); dyslipidemia (1); Esophageal atresia (1); extraskeletal osteosarcomas (1); fibromatosis (1); Fibroxanthoma (1); geleophysic dysplasia (1); genetic disorder (1); Hajdu-Cheney syndrome (1); head and neck cancer (1); hepatocellular carcinoma (1); hypertriglyceridemia (1); hypochondroplasia (1); hypotrichosis (1).
A further 43 diseases each share a sentence with TRPS1 in 1 paper.